MMP2 (matrix metallopeptidase 2)
Diseases named in the same sentence as MMP2 in open-access papers (continued):
Sharing a sentence is not in itself a finding about the gene and the disease.
tumor (continued). "Furthermore, CUL7 silencing induced the downregulation of the expression of MMP2 and MMP9, matrix metalloproteinase (MMP) family proteins that play important roles in ECM degradation and in the migration and invasion of tumour cells." (PMID 32252802, 2020). "Performed in silico analysis let us hypothesized that SM can control EMT of tumor cells by direct interactions with JNK1 and MMP-2/-9." (PMID 33327637, 2020). "MMP production in many cancers is elevated in the surrounding stromal tissue, but not in the tumor, and cases of metastasis are correlated with higher levels of MMP-2 mRNA in surrounding healthy tissue." (PMID 33198257, 2020). "In summary, the present study demonstrated the anti-tumor effects of MT on the HCC, and MT suppressed HCC progression possibly via regulating proliferation- and migration-related mediators including c-Met, p-AKT, NF-κB, MMP2, and MMP9 in HepG2 cells." (PMID 32117722, 2020). "In addition, many studies have identified that MMP2 and MMP9 are closely related to tumour migration and invasion and explained the mechanism." (PMID 33128353, 2020). "Moreover, the activation of ERK can increase the expression of invasion-related genes, including MMP-2 and MMP-9, thereby promoting the invasion and migration of tumor cells." (PMID 32049100, 2020). "Additionally, the protein expressions of MMP-2 and MMP-9, crucial for tumor invasion, exhibited an identical pattern of Jagged2 among the four groups." (PMID 32792862, 2020). "Similarly, the transformation of Ppdf-Gd-based nanoparticles to nanotubes triggered by MMP-2-cleavage, effectively improved the accumulation and retention of a GD-based contrast agent (Gd-DOTA) in the tumor." (PMID 32751865, 2020). "Of them, MMPs, MMP2, MMP3 and MMP9 could induce tumor cell invasion and migration by promoting the degradation of extracellular matrix, such as collagen." (PMID 32924971, 2020). "Because HN4 and HN12 cells are derived from a stage IV tumor, EEOS may regulate their invasiveness by targeting their MMP-2 and MMP-9 activity." (PMID 32102512, 2020). "Then we confirmed whether matrine can also affect CXCR4, MMP-2, and MMP-9 mRNA levels in tumor cells." (PMID 32630806, 2020). "MMP2 and MMP9 are the two critical MMPs that mediate tumor cell invasion." (PMID 32420351, 2020). "Further studies in which the expression of MMP2 in isolated CTC is evaluated, in parallel to TSPAN1, are required to confirm the potential role of TSPAN1 in migration of cancer cells via blood to distinct tumor metastatic sites." (PMID 35582043, 2020). "First, imipramine may inhibit ERK/NF‐κB signalling transduction and thus reduced tumour progression‐related proteins expression, including MGMT, MMP‐2, MMP‐9, uPA, VEGF, Cyclin D1 and XIAP." (PMID 32149465, 2020). "It is generally accepted that MMP-2 and MMP-9 are involved in tumor metastasis." (PMID 32978501, 2020). "Additionally, MMP-2 and MMP-9 released by MCs are capable of facilitating the tumor vascularization and promoting tumor invasiveness, respectively." (PMID 31256327, 2020). "Moreover, the miR-31-5p mimics and si-PEX5 decreased the levels of MMP2 and MMP9, key molecules mediating tumor cell invasion." (PMID 32373215, 2020). "In addition, CAFs were significantly enriched in tumor vessel proximity and showed an increased expression of VEGF-α, Matrix Metallopeptidase 2 (MMP2), MMP9, basic Fibroblast Growth Factor (bFGF), and TGF-β." (PMID 32235370, 2020). "Among MMPs, MMP2 and MMP9 have pivotal role in angiogenesis, tumor proliferation, and invasion." (PMID 31929760, 2020). "Additionally, the protein expressions of MMP-2 and MMP-9, two proteolytic enzymes of matrix metalloproteinases (MMPs) frequently playing a critical role for tumor invasion and distal metastasis, exhibited an identical pattern of Jagged2 among the three groups." (PMID 32792862, 2020).
tumor (continued). "GB is a highly invasive tumor, interestingly we found that hypoxia did not induce MMP-2, MMP-9, PLAU, uPAR, CTSA, or ANXA2 gene transcription in our GB cell models." (PMID 32867190, 2020). "In light of these data, Ezrin represents a key regulator of tumor metastasis progression for its ability to regulate cell migration promoting EMT and to enhance the invasion capability through up-regulation MMP-2 and MMP-9 transcriptional and translational levels via the AKT signalling pathway." (PMID 33003361, 2020). "MMP-2 and MMP-9 activity is important in initiating tumor invasion." (PMID 32102512, 2020). "We detected MMP2, which is secreted as a proprotein, at high abundance in tumor biopsies but not in the DFTD cell line." (PMID 30645971, 2019). "RT-qPCR assays revealed that the expression of maspin affected the gene expressions of cyclin D1, p21, vimentin MMP2, and MMP9 in xenograft tumors, which suggested that maspin may modulate these genes to regulate tumor growth in vivo." (PMID 31861435, 2019). "SHMT1 acts as a tumor suppressor in HCC by inhibiting cell metastasis, EMT and MMP2 production." (PMID 30755243, 2019). "In fact, EVs released by renal CSCs and not by differentiated tumor cells enhance the formation of lung metastases by the upregulation of MMP2, MMP9 and VEGF receptors by lung endothelial cells." (PMID 31013896, 2019). "MMP-2 and MMP-9 participate in both early and late processes of tumor progression." (PMID 31839881, 2019). "Upon histological evaluation, the tumor population and the levels of active STAT3, Bcl-xL, and pro-MMP-2 were elevated, and that of active caspase-3 was decreased in the vehicle-treated mice, indicating that the cancer cells were actively growing in this group." (PMID 31684051, 2019). "Finally, we measured in prostate tissue obtained from WT, CLUKO, TRAMP, and TRAMP/CLUKO, the expression and activity of ECM metalloproteinases (MMP-2 and MMP-9) that are known to be involved in tumor dissemination being regulated by the NF-κB pathway." (PMID 31885575, 2019). "MMPs, especially MMP-2 and MMP-9, play crucial roles in tumor invasion and metastasis." (PMID 30915362, 2019). "MMP-2 and MMP-9 expression in the tumor was further detected by a western blot assay (d e)." (PMID 31637006, 2019). "Moreover, β-catenin can increase the transcription of downstream β-catenin signaling pathway-related genes, including VEGF, MMP2, and MMP7, thereby leading to tumor cell proliferation and metastasis." (PMID 31004081, 2019). "The mentioned study also showed that the prognostic value of MMP-2/MMP-9 overexpression was independent of other tumor prognostic factors like tumor size, depth, and the number of lymph nodes involved in lymph node metastasis." (PMID 31582999, 2019). "Furthermore, the expressions of MMP-2 and VEGF involved in metastasis, as well as inflammatory genes IL-1β, IL-6 and IL-10, showed dose-dependent decrease in tumor tissue after cisplatin exposure." (PMID 32257905, 2019). "The MMP-2 substrate acts as active targeting to the TME due to the overexpression of metalloproteinases and the cis-aconityl linkage allows for controlled release of DOX on site due to the tumor acidic hydrolyzed of the bonds." (PMID 31475143, 2019). "This compound demonstrates activity against HCC, preventing the exaggerated formation of ROS and assisting in the killing of tumor cells through DNA oxidation, as well as angioneogenesis by acting to reduce VEGF-induced vascularisation and suppression of MMP-2 and MMP expression−9." (PMID 31293975, 2019). "Immunofluorescence analyses validated the expression of mesenchymal markers, N-cadherin, MMP-2 and MMP-9 were suppressed in mice tumor tissues; whereas the expression of epithelial marker, E-cadherin was increased in mice tumor tissues after treatment of mice with WZ35." (PMID 31703744, 2019).
tumor (continued). "Assessment of MMP-2 and MMP-9 expression in the invasive tumor front may be helpful in the differentiation of verrucous carcinoma and squamous cell carcinoma of the oral cavity." (PMID 31344926, 2019). "Moreover, MMP-2 and MMP-9 are crucial for angiogenesis and are possibly correlated with tumor growth." (PMID 30621167, 2019). "The balance between MMP2 and TIMP2 plays a key role in tumor cell invasion and metastasis." (PMID 31598171, 2019). "These biomarkers include ADAM17, MMP2, MMP9, and MMP11, survivin and CK19, vimentin, CXCR4, ING5, and Stanniocalcin2; in all of these examples, these molecules are overexpressed in tumoral GC tissues." (PMID 31249523, 2019). "It is proposed that propranolol inhibits vasodilation via beta-receptors, which decreases blood flow to the lesion; blocks the release of proangiogenic factors (e.g., VEGF, bFGF, MMP-2, and MMP-9), thus limiting the growth of IH; and induces apoptosis in endothelial cells, favoring tumor remission." (PMID 31700578, 2019). "ZR30 prevents MMP2 activation, thus limiting tumor invasion, blocking EGFR/Notch/AKT signaling, exerting an anti-tumor effect on different Glioblastoma cell subpopulations in a mouse model miming intratumor heterogeneity." (PMID 30832246, 2019). "However, the administration of ODZ10117 remarkably suppressed the tumor population and the levels of active STAT3, Bcl-xL, and pro-MMP-2, and increased the level of active caspase-3." (PMID 31684051, 2019). "For Caov3 cells, there was still nearly no radioactivity of 18F-NOTA-CREKA in tumor cells, no matter with or without the activation of MMP-2." (PMID 31346326, 2019). "Excessive expressions of N-cadherin, MTA1, MMP-2, and MMP-7 also facilitate tumor metastasis." (PMID 31189744, 2019). "Despite the lack of significance, a higher expression of MMP-2 in stroma and tumor was observed in patients who survived in 3 and 5 years, and an inverse correlation for the expression of MMP-9, which was confirmed based on the literature." (PMID 31223594, 2019). "Thus, E-cadherin, N-cadherin, vimentin, MMP2 and MMP9 were identified as attractive cancer targets that all play important roles in the context of tumour metastasis." (PMID 31423109, 2019). "MMP2 and MMP9 are closely involved in tumor invasion and migration in many malignant tumors." (PMID 31263453, 2019). "Additionally, expression of only three proteins, namely TGF-α, IGF2, and MMP-2, was significantly elevated in the metastatic CRC group, independently of the other variables (e.g., tumor classification, histological grade, and patient age)." (PMID 31623387, 2019). "We examined the interaction among HE4, ANXA2 and MMP2 in various malignant tumor cell lines and the tool cell line HEK293, according the results, it was inferred that HE4, ANXA2, and MMP2 might form a protein complex." (PMID 31210752, 2019). "MMP2 and MMP9 are known to play a role in angiogenesis, tumor growth and metastasis." (PMID 30871117, 2019). "Furthermore, H&E and IHC analyses revealed that the invasive border of the tumor and the expression of NKCC1, vimentin, and MMP2 were decreased in the U87‐Sh groups, which is consistent with the in vitro results." (PMID 30159893, 2019). "MMP2 and MMP9 are important protein pathways for tumor invasion and metastasis." (PMID 31110076, 2019). "However, in the analysis of 5-year survival, MMP-2 and MMP-9 both in tumor and stroma, as well as TIMP-1 in stroma, can be useful." (PMID 31223594, 2019). "Moreover, being able, in addition to its cytotoxic effect, to counteract both cell migration and invasion by affecting both NF-κB nuclear localization and MMP2 activity, ONC must certainly be regarded as an important tool against tumor metastasis onset." (PMID 31783660, 2019). "Present study is the continuation of our previous investigations, where we assessed whether the serum levels of MMP-2 and TIMP-2 might be used as potential tumor markers for gastric (GC), esophageal (EC) and colorectal cancer (CC)." (PMID 30719232, 2019).
tumor (continued). "CA can act by preventing the production of ROS (reactive oxygen species), inducing DNA oxidation of cancer cells, as well as reducing tumor cell angiogenesis, blocking STATS (transcription factor and signal translation 3) and suppression of MMP2 and MMP-9 (collagen IV metalloproteases)." (PMID 31293975, 2019). "Furthermore, it was demonstrated that MMP-2N, MMP-2 (T-S), and MMP-9N variables affected the presence of tumor in the lymph nodes." (PMID 31223594, 2019). "In addition, chronic stress increased the expression of VEGF, MMP-2, MMP-7 and MMP-9 in transplanted tumour tissue, and catecholamine hormones enhanced the expression of metastasis-related proteins." (PMID 31624248, 2019). "AURKA overexpression could also increase the expression of MMP-2, MMP-7, MMP-9, leading to tumor metastasis by degrading extracellular matrix proteins." (PMID 31706255, 2019). "Since tumor cells dissolve Matrigel by secreting matrix metalloproteinases, we used the Western blotting assay and found that knocking down KIF20A can decrease the expression of MMP2 and MMP9 in C4-2 cells." (PMID 31565099, 2019). "Additionally, a cooperative effect of MMP-2 and MMP-9 was demonstrated in an in vivo experimental model establishing the angiogenic phenotype and invasiveness of tumor keratinocytes." (PMID 31921634, 2019). "Moreover, knockdown of CLEC5A downregulated protein level of MMP‐2, MMP‐9, PCNA and Akt phosphorylation in tumour tissues." (PMID 30834619, 2019). "MMP-2, MMP-9, and uPA are thought to play important roles in the degradation of ECM proteins, which is a key factor in tumor metastasis and invasion, and inhibition of their protein expressions and proteolytic activities can be an important strategy to prevent tumor metastasis and invasion." (PMID 31783709, 2019). "For these tumor types, five cancer drivers were targeted only by NPs at < 100 nM, including Adenylate Cyclase 1 (ADCY1), Matrix Metallopeptidase 2 (MMP2), Aryl Hydrocarbon Receptor (AHR), Cyclin Dependent Kinase 2 (CDK2), and Mitogen-Activated Protein Kinase 11 (MAP3K11)." (PMID 31214023, 2019). "Exosomal lnc-matrix metalloproteinase 2-2 (lnc-MMP2-2) mediated by TGF-β upregulates the expression of MMP2 in lung cancer cells by its enhancer activity, which leads to increasing migration and invasion of tumor cells via the increasing vascular permeability." (PMID 31355262, 2019). "Inhibition of EZH2 by ZLD1039 or miR-26a no longer induces tumour invading factors such as metalloprotease 2 and 9 (MMP2/9) and those related to epithelial-mesenchymal-transition (EMT) and, in contrast, induces differentiating factors." (PMID 29853899, 2018). "Our western blot analysis did show that MMP-2 was upregulated in the tumor area and not in normal brain parenchyma." (PMID 30670934, 2018). "MMP-2 and -9 have been recognized as major contributors to the proteolytic degradation of ECM during tumor invasion and their elevated expression is positively correlated with tumor progression, metastasis, and poor overall prognosis." (PMID 29903032, 2018). "Additionally, MMP7 is able to convert proMMP2 to active MMP2 and proMMP9 to active MMP9 thereby facilitating macrophage-tumor-stromal cell cross-talk." (PMID 29581841, 2018). "Additionally, human GBM samples express high levels of MMP-2 and MMP-9 as compared to normal brain tissues, and these levels increased with tumor progression." (PMID 30441761, 2018). "MMP-2 and MMP-9 can degrade type IV collagen, which contributes to tumor invasion and metastasis." (PMID 29977159, 2018). "Therefore, the activity or amount of MMP-2 and MMP-9 in tumor tissues is often used as tumor indicator in terms of activity and severity." (PMID 30558243, 2018). "Gga-miR-130b-3p inhibited the expression level of MMP2 and MMP9, which indicates that this miRNA may be involved in MD tumor transformation through suppressing cell invasion." (PMID 29849932, 2018).
tumor (continued). "Furthermore, xenograft tumor models were established to verify the effects of miR‐144‐3p on tumor formation and EZH2, VEGFA, MMP2 and MMP9 expressions in vivo." (PMID 30280514, 2018). "In conclusion, extracellular SNCG binds β1 integrin on tumor cells and increases levels of activated β1 integrin, FAK, MMP-2, and protein secretion from tumor cells, which promotes β1-FAK signal pathway, remodels cell microenvironment matrix and subsequently affects tumor cell motility." (PMID 29903032, 2018). "In addition, our results indicate that knockdown of TIGAR reduces the expression of MMP2 and MMP9, which play important roles in the formation of tumor microenvironments and in the promotion of cancer progression and metastasis." (PMID 29753331, 2018). "In CSCCs, tumor cells with COL7A1 knockdown manifested increased migration and higher invasiveness, accompanied by the alteration of EMT marker expression (the decreased expression of E-cadherin and the increased expression of MMP2 and vimentin)." (PMID 29499655, 2018). "Furthermore, in CP-treated cells, we detected the decreasing expression of MMP-2 and MMP-9, which are necessary for tumor metastasis." (PMID 30149677, 2018). "High expression of MMP-2 and MMP-9 can enhance the invasion and metastasis ability of tumour cells." (PMID 29751513, 2018). "Besides, treatment of BA treatment of mice with BA inhibited the expression of MMP-2, MMP-9 and P-Stat3 in 4T1 tumor tissues." (PMID 29423083, 2018). "Indeed, mRNA expression of human MMP-2, MMP-9 and MMP-14 (MT1-MMP) was upregulated by PTX treatment and MT1-MMP protein became abundant in E-cadherin- mesenchymal tumor cells." (PMID 29507310, 2018). "Since MT5-MMP activates progelatinase A in tumor tissues and facilitates tumor progression, we then sought to explore whether SNCG-stimulated motility was mediated by activation of MMP-2." (PMID 29903032, 2018). "To determine whether andrographolide regulates the expression of MMPs, we then measured MMP-2 and MMP-9 levels in the supernatant of in vitro cultured tumor cells by using gelatin zymography analysis." (PMID 30359388, 2018). "Moreover, IL-32 by promoting production of MMP2, MMP9, IL-8, and VEGF facilitates invasion as well as migration of tumor cells." (PMID 30402092, 2018). "Matrix metalloproteinase 2 (MMP2) and MMP9 possess ability to hydrolyze components of the basement membrane, and thus could promote tumor metastasis." (PMID 29880874, 2018). "Patients with high MMP-2 had greater risks of developing a larger tumor (size >1 cm, p<0.001), CLNM (p = 0.002), LLNM (p = 0.046), extrathyroidal invasion (p = 0.004), and advanced TNM stage (p = 0.011) than those with low MMP-2." (PMID 29949618, 2018). "Since MMP-2 and -9 gelatinolytic activities can degrade types IV and VII collagens, the principal components of the epidermal basement membrane, UV-induced gelatinolytic activities play a prominent role in the UV-induced skin damaging process." (PMID 29755556, 2018). "However others, employing the human choriocarcinoma cell line, JEG-3, showed that IL-12 reduced the mRNA and protein expression levels, and also the enzymic activity of both MMP-2 and MMP-9, leading to suppression of tumour cell motility and invasion." (PMID 29555826, 2018). "A series of studies demonstrated that enzymes such as MMP-2, MMP-9, and uPA generated by tumor cells participated in the proteolytic degradation of the EMC, disrupted the paratumoral anatomy, advanced tumor cells' further penetration, and led to PNI of SACC, eventually." (PMID 30430081, 2018). "MMP-2 has also been shown to be responsible for the shedding of the MHC class I polypeptide-related sequence A (MICA), which is important for stimulating natural killer (NK) and T-cell anti-tumor immunity." (PMID 29874869, 2018).